WT1 (WT1 transcription factor)
Diseases named in the same sentence as WT1 in open-access papers (continued):
Sharing a sentence is not in itself a finding about the gene and the disease.
tumor (continued). "The smaller subset is characterized by loss of the WT1 tumour suppressor gene often together with oncogenic mutations in CTNNB1, the gene encoding β-catenin, and these tumours tend to be found associated with intralobar nephrogenic rests." (PMID 23239670, 2013). "18F-FDG PET/CT imaging of Wt1-Igf2 mice using delayed image acquisition protocol provided further characterization of tumor glucolytic activity." (PMID 22875335, 2013). "Tumor growth decreased, Th1 type cytokines were detected and WT1-126-specific, IFNγ-producing lymphocytes developed in all immunized groups." (PMID 23394714, 2013). "The Wilms tumor gene, Wt1, is specifically expressed in Sertoli cells (SCs) which support spermatogenesis." (PMID 23935527, 2013). "We have previously demonstrated that the WT1 RNA expression was significantly lower in ccRCC compared to tumour-free renal cortical tissue, indicating that down-regulation of WT1 acts as a tumour suppressor in ccRCC." (PMID 23484026, 2013). "In this tumor model, somatic inactivation of the Wt1 gene occurs in the context of bi-allelic over-expression of the Igf2 gene in a small subset of differentiating metanephric mesenchymal cells." (PMID 22875335, 2013). "All five of the identified genes (DLK1, PLAGL1, SLC22A18, TP73, and WT1) have presumed tumor suppressing functions and taken together demonstrate a strong tendency towards higher methylation at the CpG sites assessed." (PMID 23890537, 2013). "Assessments of TCR redirected human T cells in immunodeficient mice injected with human WT1 expressing tumour cells have previously demonstrated the potency of retroviral modified T cells in vivo, including T cell homing and tumour eradication." (PMID 23840834, 2013). "Other tumor suppressors, such as RB1 and WT1, were also activated in these cells, consistent with multiple tumor suppression pathways being activated following introduction of physiological Wnt/β-catenin signaling in HONE1 cells." (PMID 24073846, 2013). "This will require further research to determine the function of WT1 in tumor invasion and metastasis." (PMID 23936312, 2013). "So WT1 is a universal tumor antigen and consequently a good therapeutic target for the development of gene therapy strategies." (PMID 24228711, 2013). "At the protein level a fusion of the amino-terminal domain (NTD) of the EWSR1 gene and three of the four carboxyl-terminal zinc fingers of the WT1 tumour suppressor gene takes place." (PMID 22587803, 2012). "WT1 is an oncogenic protein expressed by the Wilms' tumor gene that is overexpressed in the majority of acute myelogenous leukemias (AMLs) and CML." (PMID 23241263, 2012). "In hematologic malignancies, TCR specificity for WT1 peptides, a peptide from the EB virus, and a DLBCL-associated antigen were transferred into donor T cells and displayed specificity against tumor cells expressing specific LAAs." (PMID 23241263, 2012). "The Wilms tumor suppressor (Wt1) can upregulate EPO gene expression, and its colocalization with EPO in developing mice has led to the suggestion that Wt1 contributes to EPO gene regulation in hepatocytes and neuronal cells of the dorsal root ganglia." (PMID 22567318, 2012). "Overexpression of EGR1 has been reported to increase proliferation, enhance tumor growth and antagonize the effects of the tumor suppressor Wilms tumor 1 (WT1) in baby rat kidney cells." (PMID 23029358, 2012). "WT1 is firstly thought to function as tumor suppressor, but the following wildly studies support that WT1 acts as oncogene." (PMID 22449094, 2012). "Here we show that removal of a single gene, the Wilms' Tumour gene, Wt1, in the adult mouse leads to the extremely rapid deterioration of multiple tissues." (PMID 22216009, 2011). "WT1 is firstly thought to function as tumor suppressor, but the following wildly studies support that WT1 act as oncogene." (PMID 22133358, 2011).
tumor (continued). "Depending on the cell type being investigated, WT1 can either activate Bcl-2 and function as an oncogene or suppress Bcl-2 and function as a tumor suppressor." (PMID 22133358, 2011). "Mice deleted for the Wilms' tumour gene, Wt1, lack kidneys, gonads, and spleen and die at mid-gestation due to defective coronary vasculature." (PMID 22216009, 2011). "Since WT-1 is a potentially useful tumor antigen, a number of clinical trials have evaluated WT-1 peptide based vaccines." (PMID 24213121, 2011). "WT-1 (Wilms' tumor gene 1) is a cancer antigen that is required for tumorigenesis, expressed in a high percentage of tumor cells and rarely expressed in adult normal cells." (PMID 24213121, 2011). "In conclusion, this study strongly suggests that WT1 can act as a tumour suppressor in ccRCC-regulating hTERT gene expression via multiple pathways." (PMID 20842112, 2010). "We show that endogenous WT1 in tumor cells is cleaved following cytotoxic drug treatment and demonstrate that this cleavage is HtrA2 dependent." (PMID 20122399, 2010). "WT1 is known to be a potent transcriptional regulator of many downstream targets, and can thus function as a tumour suppressor or an oncogene depending on cell type and tumour entity." (PMID 20842112, 2010). "WT1 mRNA levels were analysed in 73 ccRCC specimens and 26 tumour-free renal cortical tissue samples using qRT–PCR." (PMID 20842112, 2010). "Additional PEA3 family target genes implicated in neoplasia include; urokinase plasminogen activator (uPA), vimentin, cyclooxygenase-2 (COX-2), Twist, MUC4, WT1, osteopontin, mammaglobin, cyclin D3 and HER2." (PMID 20107508, 2010). "The collected data indicated that WT1 can control hTERT expression via multiple pathways and thereby act as a tumour suppressor in ccRCC." (PMID 20842112, 2010). "Our results suggest that WT1 can act as a tumour suppressor in ccRCC via multiple pathways leading to downregulation of hTERT." (PMID 20842112, 2010). "In 1990, WT1 was discovered as a tumour suppressor gene in Wilm's tumour, a childhood kidney neoplasm." (PMID 20842112, 2010). "In contrast to these observations, we here found significantly lower WT1 RNA levels in ccRCC samples compared with tumour-free renal cortical tissue." (PMID 20842112, 2010). "Transcriptional activation of ETS1 by WT1 has been reported in tumour vascularisation via regulation of endothelial cell proliferation and migration." (PMID 20842112, 2010). "The WT1 protein is a transcription factor critically involved in tumor cell proliferation, making it a suitable target for therapeutic strategies including vaccine approaches." (PMID 20092642, 2010). "WT1 activates the PDGFA gene in desmoplastic small round-cell tumor, which contributes to the fibrosis associated with this tumor." (PMID 19737418, 2009). "The fusion efficiency was determined by dual expression of tumor marker, WT1, and DC marker, HLA-DR." (PMID 18793383, 2008). "Many predicted targets are consistent with the known biology of their regulators, and new targets for the Wilms' tumor regulator, WT1, are proposed." (PMID 18564415, 2008). "In contrast, in HPL1D, TGF-β regulates tumour suppressor genes like WT1, ECM proteins like collagen which are responsible for arrest of cell growth and apoptosis." (PMID 17425807, 2007). "CD8+ WT1-specific CTLs were also detected in peripheral blood or tumor-draining lymph nodes of cancer patients." (PMID 17619750, 2007). "For survival the HR of WT1 staining, adjusted for residual tumor and chemotherapy response, was 1.98 (95% CI 1.28–3.79), and for recurrence-free survival the HR was 3.36 (95% CI 1.60–7.03)." (PMID 16606472, 2006).
tumor (continued). "In summary, genetic alterations of WT1 such as LOH or WT1 homozygous deletion were found in a total of eight tumours, and epigenetic alterations (i.e. reduction of WT1 expression) were found in six." (PMID 16909133, 2006). "We subjected the promoter regions of two genes residing at 11p, namely the tumour-suppressor gene WT1 (Wilms' tumour gene) (11p13) and the calcitonin gene (11p15.5), to methylation analysis in human sporadic colorectal cancer using genomic sequencing." (PMID 9365158, 1997). "We have analysed the recently cloned WT1 gene from the 11p13 region exon-by-exon in five tumours previously shown to have undergone LOH for the 11p13 region, using single strand conformation polymorphism analysis (SSCP) and PCR sequencing." (PMID 8390282, 1993). "WT1 positivity demonstrated a distinct distribution across tumor subtypes." (PMID 41930078, 2026). "In normal hematopoiesis, WT1 is thought to play a tumor suppressor role." (PMID 40507300, 2025). "Notably, patient 9, whose tumor was a cancer-type APT with a double somatic CDC73 mutation, exhibited positive WT1 staining as well as a loss of parafibromin." (PMID 40434298, 2025). "All 13 DSRCTs harboured the EWSR1::WT1 oncogenic fusion and the unsupervised analyses on the expression profiles revealed the 13 cases as a specific and biologically homogeneous cluster among the other tumours." (PMID 39921935, 2025). "Besides its roles in cell growth and differentiation, as both tumor suppressor and oncogene, WT1 regulates dormancy of early progenitors and directs differentiation towards myeloid lineage." (PMID 40299403, 2025). "This might be related to the recognition of tumor antigens [epitopes like Wilms tumor 1(WT-1), proteinase-3, cancer-testis antigens (CTAs)] by specific anti-tumoral CD8+ T cells that target clonal hematopoietic cells and inhibit disease evolution." (PMID 40227622, 2025). "WT-1 immunostain is a sensitive marker for this tumor, and when it is positive, it strongly suggests the diagnosis which may be confirmed using molecular tests." (PMID 40722508, 2025). "Finally, Wt1 is a transcription factor critical for normal embryonic kidney development and in adulthood; it, generally, acts as a tumor suppressor." (PMID 40332109, 2025). "DCs present WT1 antigens to induce specific CTLs to kill tumor cells." (PMID 41200280, 2025). "This could possibly be useful in the case of MRD where remaining NFAT GMCAR WT1TCR BiTE cells would reactivate upon contact with WT1-positive tumor cells, proliferate, and eliminate the malignant remnants." (PMID 40735486, 2025). "The piggyBac transposon vector used for gene modification of T cells expresses a T-cell receptor specific to the WT1 tumour antigen, an NFAT promoter-regulated CAR specific to GM-CSF receptor, a CD3xCD33 bispecific T-cell engager, and a truncated EGFR suicide gene system." (PMID 40735486, 2025). "The WT1 gene is a tumor suppressor and it’s overexpressed in several solid and non-solid neoplasms." (PMID 38966177, 2024). "The CpG island (CGI) of the tumor‐suppressing gene WT1 was hypermethylated in MTF_43." (PMID 38970307, 2024). "In particular, double dendritic cell vaccine therapy with WT1 and α-galactosylceramide-pulsed dendritic cell may provide an anti-tumor immune effect that is superior to that of the respective monotherapy." (PMID 39035592, 2024). "Similarly, another study utilized a kidney organoid-on-chip model to test the off-target effects of a bispecific antibody targeting the RMF peptide, derived from the intracellular tumor antigen Wilms’ tumor 1 (WT1)." (PMID 38711620, 2024). "If the clonal expansion of WT1-specific CTLs in the PB of patients is demonstrated, the clonal expansion of CTLs may also exist in tumor-draining lymph nodes (LNs) that are non-tumor sites, such as the PB." (PMID 39509060, 2024).
tumor (continued). "Given that previous studies suggest that WT1 may play a role in regulating the presence of immune cells in the tumor microenvironment, the spatial relationship between expression of WT1 and LANA and immune cell infiltrates was examined." (PMID 38190392, 2024). "The delivery system precisely and efficiently targeted tumor cells for WT1 mRNA vaccine delivery." (PMID 38742454, 2024). "WT1 shows tumor-specific overexpression and the ability to elicit active and humoral immunity." (PMID 38280040, 2024). "WT1 acts as tumor-suppressor as well as oncogene in diverse cancers." (PMID 38370381, 2024). "The delivery system accurately and efficiently targeted tumor cells for WT1 mRNA vaccine delivery." (PMID 38742454, 2024). "When considering other tumour types in a pan-cancer analysis, LF2 was also associated with the EMT (P < 1.0 × 10−307) and FN1_TAM signatures (P < 1.0 × 10−307), as well as WT1 expression (P = 5.0 × 10−09) across tumour types, independent to ccRCC tumours (Dataset EV5)." (PMID 39592856, 2024). "WT1 may be a significant prognostic marker indicating mesenchymal dedifferentiation and increased tumor aggressiveness, while TDs, known for their role in cutaneous tumors, have demonstrated a novel expression pattern in RCCs." (PMID 38929778, 2024). "Additionally, WT1 is highly immunogenic, as both peptide-based and DNA-based immunizations have been shown to be effective in inducing WT1-specific cytotoxic T lymphocytes, capable of more easily identifying and destroying WT1-positive tumor cells." (PMID 38929778, 2024). "Importantly, the WT1 helper peptide can significantly contribute to tumor eradication not only through helper CD4+ T cells but also WT1-specific CD8+ CTLs in antitumor immunity." (PMID 38336778, 2024). "In their report WT1 expression was assessed with IHC staining using a monoclonal anti-WT1 antibody (clone 6f-H2) and samples were scored as positive (WT1 overexpression) when more than 10% of tumor cells were stained in either their cytoplasm or nucleus." (PMID 38966177, 2024). "This clonality may indicate the existence of a tumor immune surveillance system involving WT1-specific CD8+ T cells." (PMID 39509060, 2024). "An implication of our observations is that immunotherapy directed towards WT1 in KS may target KS spindle cells overexpressing WT1 and potentially aid in reversing the immunosuppressive tumor microenvironment." (PMID 38190392, 2024). "Key genes implicated include WT1, which is associated with syndromic presentations such as WAGR syndrome and CTNNB1, with non-syndromic cases displaying a spectrum of mutations impacting tumor behavior and response to therapy." (PMID 39062028, 2024). "Furthermore, translation of the WT1 mRNA occurred in tumor cells, which considerably improved the expression of the WT1 protein." (PMID 38742454, 2024). "WT1 protein plays several oncogenic roles including involvement in cancer cell growth, resistance to apoptosis, enhancement of cell migration and tumor vascularization." (PMID 38966177, 2024). "Another gene downregulated by ~nine-fold in GEN-treated TM4 cells is Usp18 (Ubiquitin specific protease 18), shown to promote proliferation and be negatively regulated by Wt1 (Wilms tumor gene), a transcription factor that plays a role in spermatogenesis and in inhibiting interferon signaling." (PMID 37443838, 2023). "WT1 expression in tumor cells and HLA-A was examined after obtaining consent for testing." (PMID 36672344, 2023).
tumor (continued). "The effects of combination treatment with DSP-7888 Emulsion and an anti–programmed cell death protein 1 (PD-1) antibody on tumor volume and the frequency of tumor-infiltrating WT1-specific T cells were assessed in HLA-I transgenic mice implanted with WT1 antigen-positive tumors." (PMID 36138335, 2023). "Collectively, these data indicate that CD8+ T cell-restricted peptides originating from self-tumor antigens like hTERT and WT-1 activate not only self-reactive CD8+ T cells but also are likely to cross-activate CD4+ T cells, including Foxp3+ Treg cells with self-reactive TCRs." (PMID 37761976, 2023). "As an example of an additional EMT inducing factor, we focused on Wilms Tumour (WT1)." (PMID 36864480, 2023). "Thus, targeting WT1 can serve as a promising approach to restrict tumor growth by inhibiting angiogenesis and chemoresistance." (PMID 38173713, 2023). "Moreover, Cell Counting Kit-8 (CCK-8), colony formation, transwell, dual luciferase reporter assays and in vivo xenograft tumour growth experiments were conducted to explore the function and mechanism of WT1 in NSCLC." (PMID 37667197, 2023). "Next, we sought to determine whether WT1 TED2s could elicit enhanced cytotoxicity against tumor cells." (PMID 38022650, 2023). "Some tumor sections were immunostained with ready-to-use primary antibodies against broad-spectrum cytokeratin (CK), vimentin, calretinin, Wilms tumor gene-1 (WT-1), D2–40, Paird box 8, synaptophysin, chromogranin-A, inhibin-α, S-100, Melan-A, HMB45, CD34, and Ki-67 (Maixin, Fuzhou, China)." (PMID 38115250, 2023). "Despite this, by looking at the immune reactivity observed in both infiltrated T cells and organoid cells, we hypothesize that also WT1 T cells induced on-target off-tumor toxicity against cells within the kidney organoids." (PMID 36816758, 2023). "Metanephric adenomas are tumors of epithelial origin, and the tumor cells are positive for WT-1." (PMID 37454137, 2023). "Through comprehensive in vitro and in vivo assays, we speculated that WT1 acted as a potent tumour promoter by facilitating NSCLC cell proliferation, survival, invasion and tumorigenesis." (PMID 37667197, 2023). "Tumor size reduced significantly in the B. longum 420 group than in the B. longum 105-A and 2012 groups (P < 0.00 l each), indicating B. longum 420’s antitumor activity via WT1-specific immune responses." (PMID 35699757, 2023). "Importantly, WT1 restoration attenuated the tumour suppressing effects of miR-498-5p in vitro and in vivo, once more illustrating the oncogenic activities of WT1 in NSCLC cells." (PMID 37667197, 2023). "The WT1 gene is specifically expressed in many solid and hematological tumor cells, and whether WT1 is a tumor suppressor or a proto-oncogene has always been controversial." (PMID 38028542, 2023). "The high expression rate of the WT1 protein in tumor cells indicates that cancer immunotherapy targeting WT1 may be a therapeutic strategy for many rare cancers as an immunotherapy against a common target molecule." (PMID 36672344, 2023). "Depending on the combination with standard treatment including chemotherapy, WT1-DC may enhance anti-tumor immunity." (PMID 38143707, 2023). "When the cutoff level of the WT1-332-specific IL-10 IR index was set as 1.15, the group with a higher WT1-332-specific IL-10 released from PBMCs had a significantly lower completion rate and a higher rate of tumor progression than the group with lower WT1-332-specific IL-10 released from PBMCs." (PMID 36672344, 2023). "The correlation between TCRm-mediated ADCC signaling and antigen density suggests that the therapeutic formatting of TCRm Ab could depend on the antigen expression on tumor cells, as seen for the WT1 TCRm Ab11,33." (PMID 36593402, 2023).